RAC2 (Rac family small GTPase 2)
Description:
Plasma membrane-associated small GTPase which cycles between an active GTP-bound and inactive GDP-bound state. In its active state, binds to a variety of effector proteins to regulate cellular responses, such as secretory processes, phagocytose of apoptotic cells and epithelial cell polarization. Regulatory subunit of the phagocyte NADPH oxidase complex that mediates the transfer of electrons from cytosolic NADPH to O2 to produce the superoxide anion (O2(-)). Activates PLCG2.
Synonyms: EN-7; Gx; HSPC022; IMD73A; IMD73B; IMD73C; p21-Rac2
Tractability: Small molecule: a structure with a bound ligand is known; it has a binding pocket of medium quality. Antibody: its Gene Ontology location is reachable by antibodies, with high confidence. PROTAC: ubiquitination databases record sites on it; its protein half-life has been measured; a small molecule that binds it is known.
Target class: Enzyme; Hydrolase
Safety:
Unwanted effects reported when the protein is acted on. In parentheses: how it was acted on, where the effect was seen, and who reports it.
drug toxicity (source: ClinPGx)
Gene: Protein-coding gene on chromosome 22 (37,225,270 to 37,259,594, reverse strand). Ensembl gene ENSG00000128340.
Subcellular location: Cytoplasm
Pathways (Reactome):
Signal Transduction: PCP/CE pathway; PI5P, PP2A and IER3 Regulate PI3K/AKT Signaling; PIP3 activates AKT signaling; RAC2 GTPase cycle; RHO GTPases Activate NADPH Oxidases
Disease: Constitutive Signaling by Aberrant PI3K in Cancer
Hemostasis: GPVI-mediated activation cascade
Immune System: ROS and RNS production in phagocytes
Gene Ontology:
Molecular function: GTP binding; GTPase activity; protein binding; G protein activity; protein kinase regulator activity
Biological process: actin filament organization; lymphocyte aggregation; positive regulation of establishment of protein localization to mitochondrion; positive regulation of lamellipodium assembly; positive regulation of neutrophil chemotaxis; regulation of cell-substrate adhesion; regulation of neutrophil migration; regulation of respiratory burst; superoxide anion generation; chemotaxis; establishment or maintenance of cell polarity; regulation of cell shape; regulation of hydrogen peroxide metabolic process; respiratory burst; signal transduction; actin cytoskeleton organization; bone resorption; regulation of mast cell chemotaxis; regulation of mast cell degranulation; regulation of T cell proliferation; small GTPase-mediated signal transduction
Cellular component: actin filament; cytosol; extracellular exosome; focal adhesion; lamellipodium; NADPH oxidase complex; cytoplasmic vesicle; cytoskeleton; endoplasmic reticulum membrane; mitochondrial outer membrane; phagocytic vesicle membrane; plasma membrane; cytoplasm; membrane; nuclear envelope
Genetic constraint (gnomAD): Loss-of-function variants: 1 observed, 24.07 expected, observed/expected ratio (o/e) 0.0416, 90% interval 0.014 to 0.2. The upper end of that interval is the gene's LOEUF score, 0.2, which puts it in group 1 of 6, group 1 being the genes least tolerant of losing a copy. Missense variants: 130 observed, 258.3 expected, observed/expected ratio (o/e) 0.5, 90% interval 0.44 to 0.58. Synonymous variants: 114 observed, 109.43 expected, observed/expected ratio (o/e) 1.04, 90% interval 0.89 to 1.22.
Gene-disease validity (ClinGen):
ClinGen rates the evidence that RAC2 causes each of these diseases.
immunodeficiency 73b with defective neutrophil chemotaxis and lymphopenia (autosomal dominant): Strong.
immunodeficiency 73c with defective neutrophil chemotaxis and hypogammaglobulinemia (autosomal recessive): Moderate.
neutrophil immunodeficiency syndrome (autosomal dominant): Moderate. A primary immunodeficiency characterized by neutrophilia with severe neutrophil dysfunction, leukocytosis, a predisposition to bacterial infections and poor wound healing, including an absence of pus in infected areas.
Homologues: Orthologues: macaque RAC2 (100% identical), chimpanzee RAC2 (99% identical), mouse Rac2 (99% identical), dog RAC2 (98% identical), guinea pig RAC2 (97% identical), rat Rac2 (94% identical), pig RAC2 (93% identical), tropical clawed frog rac2 (93% identical), zebrafish rac2 (93% identical), Drosophila melanogaster Rac1 (89% identical), Drosophila melanogaster Rac2 (88% identical), rabbit RAC2 (83% identical), and 1 more. Paralogues in human: RAC1 (90% identical), RAC3 (89% identical), RHOG (71% identical), CDC42 (69% identical), RHOQ (62% identical), RHOJ (60% identical), RHOU (55% identical), RHOC (54% identical), RHOA (54% identical), RHOB (54% identical), RHOV (52% identical), RHOF (52% identical), and 10 more.
Diseases named in the same sentence as RAC2 in open-access papers:
RAC2 is named in the same sentence as 146 diseases in open-access papers, as found by Europe PMC text mining. Sharing a sentence is not in itself a finding about the gene and the disease. The quoted sentences say what the papers report.
breast cancer (26 papers, 2010 to 2025). A primary or metastatic malignant neoplasm involving the breast. "The analysis showed that GBP2 was not significantly different from the overall survival of breast cancer patients, while GPR171, DIRAS3, and RAC2 were strongly associated with the overall survival of breast cancer patients." (PMID 36212434, 2022). "The expression of DIRAS3, GPR171 and RAC2, genes associated with brain metastasis, was reduced in metastatic breast cancer, and GPR171 was found to promote brain metastasis of breast cancer cells by inducing B cells and thereby." (PMID 36212434, 2022). "In conclusion, the expressions of DIRAS3, GPR171, and RAC2 genes associated with brain metastasis were reduced in metastatic breast cancer and were strongly associated with overall breast cancer survival." (PMID 36212434, 2022). "It has been reported that RAC2 may play a key role in the regulation of the actin cytoskeleton during breast cancer metastasis and that its downregulation is associated with the invasive and metastatic capacities of human cancers." (PMID 36212434, 2022). "One study found that higher expression of RAC2, along with the other eight genes in the signature, was correlated with a better prognosis in breast cancer patients." (PMID 40565031, 2025). "In contrast, the relationship between RAC2 expression and prognosis in breast cancer appears to be more intricate." (PMID 40072059, 2025). "Expression difference analysis showed that GBP2, GPR171, DIRAS3, and RAC2 were significantly down-regulated in expression in metastatic breast cancer compared with primary breast cancer tumors." (PMID 36212434, 2022). "Only GPR171, DIRAS3, and RAC2 were strongly correlated with the overall survival of breast cancer patients." (PMID 36212434, 2022). "The analysis showed that only GBP2, GPR171, DIRAS3, and RAC2 were significantly down-regulated in expression in metastatic breast cancer compared with primary breast cancer tumors." (PMID 36212434, 2022). "This group first isolated cDNAs for Rac1, Rac2 and Rac3 genes from various breast cancer cell lines and performed Sanger sequencing on them." (PMID 32992837, 2020). "RAC2 and KRAS are 2 members of the Ras proto-oncogene superfamily, associated with breast cancer tumorigenesis and metastasis." (PMID 31481608, 2019). "RAC2 signaling events were proved to be relevant with phospholipase D-induced breast cancer cell invasion and found to regulate actin cytoskeleton during breast cancer metastasis." (PMID 32047513, 2019). "ELMO1 is associated with metastasis in several cancers, and is part of the chomokine regulated pathway, including Rac1 and Rac2, that regulates the actin cytoskeleton in metastatic breast cancer." (PMID 30557297, 2018). "P-Rex1 functions as a specific Rac1 and Rac2 activator in neutrophils, endothelial cells and breast cancer cells." (PMID 21884615, 2011). "RAC2 is part of an immune-related signature for breast cancer." (PMID 40565031, 2025). "RAC2 expression was significantly downregulated in breast cancer." (PMID 39596003, 2024). "Notably, in the present study, our results also showed that DIRAS3, GPR171, and RAC2 were less expressed in tumors that developed metastatic disease compared with primary breast cancer tumors." (PMID 36212434, 2022). "Moreover, the expression levels of DIRAS3, GPR171, and RAC2 were strongly correlated with the overall survival of breast cancer patients." (PMID 36212434, 2022). "Lastly, RAC2 polymorphism is related to cardiotoxicity in breast cancer treatment, while the function of RAC2 in MI is not known yet." (PMID 36012110, 2022). "They found that the expression of either the Rac1 or Rac2 mutant protein resulted in enhanced colony formation in soft agar and tumor formation and growth in mice, confirming the transforming capabilities of Rac1 and Rac2 in breast cancer." (PMID 32992837, 2020).
breast cancer (continued). "To further explore the biological pathways most relevant to the pathogenesis of breast cancer brain metastasis, we performed GSEA analysis on GPR171, DIRAS3, and RAC2." (PMID 36212434, 2022). "We performed expression analyses of five genes (GBP2, GPR171, DIRAS3, RAC2, CACNA1D) obtained from the LASSO model to observe their expressions in primary breast cancer and metastatic breast cancer." (PMID 36212434, 2022). "Furthermore, in this study, the primary Rac effector of neuroblastoma appeared to be Rac2, as opposed to Rac1 in melanoma, prostate cancer, breast cancer, and liver cancer." (PMID 38884093, 2024).
melanoma (11 papers, 2014 to 2025). A malignant, usually aggressive tumor composed of atypical, neoplastic melanocytes. "gp91phox, Ncf1 (p47phox), and Rac2-deficient mice all exhibit fewer lung metastases than control mice in experimental melanoma models." (PMID 28351984, 2017). "Interestingly, tumor associated activating mutations in Rac1 and Rac2 have been identified in melanoma, sarcoma, and tumors of the head and neck, breast, and brain." (PMID 30609754, 2019). "We detected RAC2 expression in several melanoma cell lines and found that RAC2 expression in 92-1 cells was much higher than that in OCM-1 cells." (PMID 31281584, 2019). "In the present work, we proposed to study the radiosensitizing effect of RAC2 on melanoma cells to further improve the treatment effects." (PMID 31281584, 2019). "In conclusion, RAC2 was found to play a role in the radiosensitization of human malignant melanoma cells by activating NADPH oxidase and facilitating the ROS production." (PMID 31281584, 2019). "We compared the expression of RAC2 in 2 human melanoma cell lines of different radiosensitivity and found that the expression of RAC2 is positively correlated with the radiosensitivity of melanoma cells." (PMID 31281584, 2019). "We observed a marked increase in metastatic foci in the lungs of WT mice compared with an 80% reduction in the number of nodules in Rac2-/- mice injected with B16F10 melanoma (p<0.001)." (PMID 24770346, 2014). "Our initial observation was that tumor growth of 4 different syngeneic tumors which included: Lewis lung carcinoma (LLC), B16 melanoma and neuroblastoma (9464D) was significantly reduced in the Rac2-/- mice." (PMID 24770346, 2014). "The results of this study are of great significance to clarify the regulatory mechanisms of RAC2 on the radiosensitivity of melanoma cells and provide an important theoretical basis for the development of clinical radiosensitization methods based on the RAC2 gene." (PMID 31281584, 2019). "In the current study, it was found that upon radiation-inducible RAC2 overexpression, which led to the increase of NADPH oxidase activity, the endogenous ROS production was promoted and the radiation-induced decrease of the survival fraction of melanoma OCM-1 cells was aggravated significantly." (PMID 31281584, 2019). "The right hemithorax (injected with WT BMDMs) showed luciferase activity and B16 metastatic nodules while there was no B16 melanoma or luciferase signal and minimal metastatic nodules detected within the left hemithorax (injected with WT GBMDM vs. Rac2-/- BMDM)." (PMID 24770346, 2014).
Immunodeficiency (10 papers, 2017 to 2026). Failure of the immune system to protect the body adequately from infection, due to the absence or insufficiency of some component process or substance. "Pathogenic RAC2 variants show significant phenotypic heterogeneity (spanning from neutrophil defects to combined immunodeficiency) across dominant, constitutively activating, dominant activating, dominant negative, and autosomal recessive subtypes." (PMID 38516355, 2024). "Loss-of-function of RAC2 causes immunodeficiency, while upregulation of this gene is a marker of poor clinical prognosis of certain carcinomas." (PMID 35371081, 2022). "Genetic mutations in RAC2 cause severe phagocytic immunodeficiency characterized by severe infection in infancy." (PMID 35145474, 2021). "In humans, Rac2 seems to act dominantly over Rac1 for antibody production since loss of Rac2 or dominant negative Rac2 leads to common variable immunodeficiency with low antibody serum titers." (PMID 29056938, 2017). "RAC2-related immunodeficiency is a rare inborn error of immunity with a broad clinical spectrum ranging from neonatal severe combined immunodeficiency to atypical combined immunodeficiency diagnosed later in life." (PMID 41685306, 2026). "Rac2 plays an essential role in T cell activation and cytoskeletal remodeling, while ENPP1 is implicated in immune disorders and cancer." (PMID 41257548, 2025). "However, benefits of Rac2 as therapeutic targets have not been previously explored, probably due to the lack of a Rac2-specific inhibitor as well as the fact that Rac2 deficiency results in primary immune deficiency and poor wound healing." (PMID 28954734, 2017).
leukemia (8 papers, 2015 to 2021). A malignant (clonal) hematologic disorder, involving hematopoietic stem cells and characterized by the presence of primitive or atypical myeloid or lymphoid cells in the bone marrow and the blood. "It has been shown that ROS production induced by Rac2 leads to DNA damage in leukemia stem cells causing genome instability suspected to drive the rapid accumulation of mutations in progenitor cells." (PMID 30976051, 2019). "This is in agreement with the previous reports from murine models, in which loss of Rac2 prevented the development of BCR-ABL-initiated leukemia by increasing apoptosis of LSCs, rather that altering their interactions with the microenvironment." (PMID 26016997, 2015). "We next questioned whether mitochondrial dysfunction might underlie the pheneotypes we observed in our human leukemia models upon RAC2 depletion." (PMID 26016997, 2015). "In order to specifically address the role of either RAC1 or RAC2 in human leukemia, we used shRNA interference strategy." (PMID 26016997, 2015). "Although studies on a wider collection of leukemic samples are necessary, these results are a first validation that RAC2 is necessary for primary human BCR-ABL-induced leukemia as well." (PMID 26016997, 2015). "Moreover, studies have shown that, during diallyl disulfide-induced apoptosis of human leukemia HL-60 cells, RAC2 is overexpressed." (PMID 33511023, 2021). "However, in already fully transformed murine MA9 leukemia cells, depletion of either Rac1 or Rac2 reduced the in vitro survival through enhanced apoptosis." (PMID 30558116, 2018). "Despite the fact that knocking down either RAC1 or RAC2 is adequate to reduce the transformed MLL-AF9 leukemia development; RAC2 but not RAC1, plays a dominant role in the initiation of acute myeloid leukemia in vivo." (PMID 33406731, 2021). "Knock out mice for Rac1 or Rac2 was sufficient to impair the survival and growth of MLL-AF9 leukemia and this could be rescued by Bcl-xl with the BH3-mimetric ABT-737." (PMID 32529062, 2020). "Deletion of Rac2 alone, but not of Rac1, delayed leukemia onset and increased the survival of the mice significantly." (PMID 30558116, 2018). "Similarly, central nervous system metastatic pre-B leukaemia cells (SD1-cells) overexpress Rac2, and when pre-treated with the Rac inhibitor, NSC23766, prior to engraftment, delayed disease establishment and significant reduction in leukaemia burden in extramedullary organs and the cranium." (PMID 34679751, 2021).
atherosclerosis (7 papers, 2021 to 2025). A disease characterized by the build-up of fatty material and calcium deposition in the arterial wall resulting in partial or complete occlusion of the arterial lumen. "It has been reported that macrophage expression of ALDH2 is conducive to limiting the persistent inflammation during atherosclerosis through the inhibition of Rac2 degradation and the promotion of macrophage efferocytosis." (PMID 40968356, 2025). "By using RNA-seq, proteomics, and immunoprecipitation experiments, we later discovered and verified Rac2 as its downstream target, demonstrating the crucial function of the ALDH2-Rac2 axis in mediating cytokinesis during atherosclerosis." (PMID 36588568, 2022). "In an atherosclerosis model, Rac2 prevented plaque calcification by suppressing macrophage IL-1β expression." (PMID 33011741, 2021). "In addition, VCAM1, NCF2, RAC2, MMP9, and ICAM1 were associated with fluid shear stress and atherosclerosis." (PMID 38640295, 2024). "Thus, the RAC2/RAC3 network may play a role in atherosclerosis and senescence—pathophysiologic processes that have been implicated in the progress of CVD in TC patients—as well as bleomycin-induced pneumonitis." (PMID 33011741, 2021). "Interestingly, ALDH2rs671 in macrophages can accelerate Rac2 degradation and promote the AMPK-mediated phosphorylation of ALDH2 to aggravate atherosclerosis." (PMID 40968356, 2025). "Then, six hub genes (COL1A1, IBSP, CTSD, RAC2, MAF, and THBS1) were obtained through the integration of multisource databases and they were all significantly upregulated in both the osteoporosis and atherosclerosis group compared with the control group." (PMID 35937806, 2022).